IL1B (interleukin 1 beta)
Diseases named in the same sentence as IL1B in open-access papers (continued):
Sharing a sentence is not in itself a finding about the gene and the disease.
mastitis (continued). "Similarly, Gardenoside alleviates S. aureus-induced mastitis by activating the Nrf2/SLC7A11/GPX4 signaling pathway, which reduces pro-inflammatory cytokines (TNF-α, IL-1β) expression and neutrophil infiltration." (PMID 41479924, 2025). "A recent in vitro study demonstrated that Lactobacillus could inhibit the expression of inflammatory cytokines (such as IL-6, IL-1β, and TNF-α), thereby preventing mastitis." (PMID 41011421, 2025). "Additionally, a recent study found that levels of IL-6, IL-1β, TNF-α, and MPO were all increased in mice that developed mastitis due to S. aureus." (PMID 41148692, 2025). "However, when mastitis occurs in dairy cows, TNF-α and IL-1β are rapidly expressed in the early stages of infection and have powerful proinflammatory functions." (PMID 40105325, 2025). "In an A. viridans-induced mouse mastitis model, a single 25-μg dose of AVPL significantly reduced bacterial loads in the mammary glands (~2-log10), alleviated mastitis-related pathological symptoms, and decreased inflammatory cytokine levels (TNF-α, IL-1β, and IL-6) in mammary tissues." (PMID 40970331, 2025). "In the course of mastitis, buffaloes increase the expression of immune genes related to the activation of pathogen recognition (TRL-2, TRL-4) and to the cytokine network (TNF-α, IL-1β, and IL-8), leading to the secretion of pro-inflammatory cytokines." (PMID 39858163, 2025). "qRT-PCR and ELISA were performed to measure the levels of IL-6, TNF, and IL-1β in the breast tissue of mice with LPS-induced mastitis, with or without ammonia treatment." (PMID 40370468, 2025). "Furthermore, it has been documented that diosmetin relieved S. aureus-induced mastitis in mice by inhibiting the expression of MPO, TNF-α, IL-1β, and NF-κB." (PMID 39199398, 2024). "Furthermore, in vivo tests indicated that intramammary infusion of L. casei 03 relieved pathological changes, reduced the secretion of IL1β, IL6 and TNFα and MPO activity in the mouse mastitis model." (PMID 38395896, 2024). "Moreover, using PPI network analysis, we determined that TNF, IL-6, IL-1β, CXCL8, and ICAM1 proteins were the main targets of GYS for mastitis treatment." (PMID 38630770, 2024). "NLRP3 inflammasome activation in subclinical mastitis and after LTA stimulation in MAC-T cells and murine mammary glands was confirmed in the present study by the upregulation of NLRP3, ASC, cleaved-caspase-1 and IL-1β." (PMID 39765775, 2024). "Similarly, rosmarinic acid and nuciferine alleviate LPS-induced mastitis by inhibiting the TLR4/MyD88/NF-κB signaling pathway and production of TNF-α, IL-1β, and IL-6 in MMECs." (PMID 39199398, 2024). "Likewise, dose-dependent decreases in several inflammatory markers during mastitis, including MPO activity, and TNF-α and IL-1β, were detected after HEX treatment compared with S. aureus treatment." (PMID 37948460, 2023). "In the murine model of mastitis, Z-d14CFR exhibits favorable therapeutic potential by enhancing the clearance of E. coli in the mammary gland, reducing neutrophils infiltration and expression of TNF-α and IL-1β." (PMID 35563007, 2022). "Moreover, SYK protein level was also significantly down-regulated in bovine mastitis tissue, and protein levels of NLRP3, TLR4 and IL-1β were significantly up-regulated." (PMID 36672605, 2022). "Moreover, the inflammation of the buffalo udder (i.e., clinical and subclinical mastitis) promoted the increase in cytokines (TNF-α, IL-6, IL-1β, and IFN-γ) production, which impaired the reproductive success in this animal." (PMID 36009715, 2022). "Luteolin inhibited the expression of TNF-α, IL-1β, and IL-6; suppressed IκBα and NF-κB p65 phosphorylation levels; and downregulated the expression of MMP-2 and MMP-9 in S. aureus-induced mastitis, showing its potential in reducing tissue damage and inflammation caused by S. aureus-induced mastitis." (PMID 36111166, 2022).
mastitis (continued). "The P2X7R significantly decreased after LPS induction in bMECs, Overall, TNFα and IL1β are likely to be mainly produced by the resident or recruited leucocytes rather than by MEC in mammary during mastitis." (PMID 35812870, 2022). "The proinflammatory cytokines IL-1β, IL-6, and TNF-α are important in mastitis." (PMID 35624447, 2022). "For example, EV downregulated the levels of IL-1β, TNF-α, and iNOS via NF-κB and MAPK signaling pathways in the lipopolysaccharide (LPS)-induced mastitis and adjuvant-induced arthritis, suppressing the production of TNF-α, IL-1β, and IL-6 in adjuvant-induced synovial inflammation in rats." (PMID 35795554, 2022). "The selection of possible regulated genes (cytokines TNFα, IL-1β, IL-6, IL-10, chemokines CCL20, CXCL8 and antimicrobial effector molecules LAP and S100A9) were adapted from a recent in-vivo study that also focussed on early inflammatory events in mastitis." (PMID 34798884, 2021). "Our research results showed that PE could significantly inhibit the increase in the levels of inflammatory mediators such as TNF-α, IL-6, IL-1β, MPO and iNOS during mastitis." (PMID 34383710, 2021). "During the process of mastitis pathogenesis, the production of pro-inflammatory cytokines is acutely induced to activate immune responses: firstly IL-8 attracts neutrophils, followed by TNF-α, interferon gamma (IFN-γ), and IL-1β induces tissue inflammation." (PMID 34827927, 2021). "Our results show that activation of GPR109A could significantly reduce the expression of N-P65, IL-6, IL-1β, and TNF-α in BMECs, thus inhibiting mastitis." (PMID 32397071, 2020). "In addition, based on published literature, we concluded that TLR4, IL-1β, IL-6, TNF-α and MYD88 are key players in NF-κB signaling and also have an essential role in mastitis development." (PMID 32927884, 2020). "Moreover, dioscin also can reduce the production of proinflammatory factors such as interleukin-1 beta (IL-1β) and inhibit the activation of NLRP3 inflammasome in LPS-induced mice mastitis." (PMID 33488936, 2020). "Studies have shown that some plant (like cepharanthine and kaempferol) could attenuate LPS-induced mouse mastitis by suppressing the production of TNF-α, IL-6 and IL-1β." (PMID 29904013, 2018). "The present study demonstrates that berberine hydrochloride exerts anti-inflammatory effects by inhibiting inflammatory cell infiltration, the production of TNF-α, IL-1β, and IL-6, and the activation of the TLR4/NF-κB signaling pathway in a mouse model of mastitis." (PMID 29849710, 2018). "Also, in an LPS-induced mouse mastitis model and in LPS-treated mouse mammary epithelial cells, GLY treatment significantly reduced MPO activity and protein expression of TNF-α, IL-1β, and IL-6." (PMID 27792814, 2016). "Another study looking at the effect of SCFP supplementation on the Streptococcus uberis mastitis challenge in mid-lactation dairy cows found no change in IL-1β or IL-6 concentrations from the time of the Streptococcus uberis challenge up to 9 days post-challenge." (PMID 39595313, 2024). "Similarly, another study reported that Brazilin (isolated from the traditional herbal medicine Caesalpinia sappan L.)suppressed TLR2, TNF-α, IL-1β, and IL-6 levels by inhibiting the TLR2/NF-κB/MAPK signaling pathways in mammary gland tissues, thus preventing S. aureus-induced mastitis." (PMID 39199398, 2024). "Moreover, we found that the SRMT group had several increases in mastitis parameters, including MPO activity, TNF-α, and IL-1β levels, compared with the control and HRMT groups; however, zanamivir treatment alleviated these increases compared with those of the SRMT group." (PMID 37069691, 2023). "Similarly, upon E. coli stimulation, gut microbiota-dysbiostic mice had more apparent mastitis characteristics compared with control mice, including increased myeloperoxidase activity, tumor necrosis factor (TNF)-α, and interleukin (IL)-1β concentrations in the mammary gland tissue." (PMID 35479637, 2022).
mastitis (continued). "It is reported that transplanting the feces of mastitic cows into sterile mice caused mastitis symptoms in mice and inflammation in the serum [increased interferon (IFN)-γ, interleukins (IL)-17, and endotoxin] and colon (increased IL-1β), which did not occur when transplanting healthy cows’ feces." (PMID 35479637, 2022). "In addition, TLR4, IL-1β, IL-6, TNF-α, MYD88 and NF-κB might be a useful addition as markers in mastitis control strategies." (PMID 32927884, 2020). "This study found that farrerol could improve pathological injury of mammary glands, attenuate the activity of MPO, inhibit the production of pro-inflammatory mediators (TNF-α, IL-6, IL-1β, iNOS and COX-2) and the phosphorylation of AKT, NF-κB p65, p38 and ERK1/2 in LPS-induced mouse mastitis." (PMID 29904013, 2018). "It is reported that researchers transplanted the feces of mastitis cows into sterile mice and found that the mice showed mastitis symptoms and caused inflammation in the serum ( IFN-γ, IL-17, and endotoxin) and colon (increased IL-1β), which did not occur when transplanting healthy cows feces." (PMID 37420170, 2023). "When studying the effectiveness of SMP against mastitis, it was found that SMP supplementation could inhibit the activities of myeloperoxidase (MPO) and N-acetyl-β-D-glucosaminidase (NAGase) and reduce the expression of IL-6, IL-1β and TNF-α inflammatory factors in rats with mastitis." (PMID 36937857, 2023). "Regarding the impact of pathogen type on the reproductive performance of cows, Gram-negative mastitis pathogens, particularly E. coli can induce a massive release of cytokines such as tumor necrosis factor-alpha (TNF-α), interleukin (IL)-1β, IL-8, and others." (PMID 41463693, 2025). "Serum IL-6 levels in the PUE-fed control healthy cows were significantly lower than those in the mastitis group (p < 0.01), and the expression of TNF-α and IL-1β also decreased, but there was no statistical significance." (PMID 37175449, 2023). "In addition to TNFa and IL-1b, CASP1 and NFKB1 were found to be up-regulated in our study suggesting that TREM1 signaling may likely provide the link between TLR2- and NLR-mediated signal transduction in cytokine-induced inflammation during the initiation of host defense such as in mastitis." (PMID 24341851, 2013). "Pretreatment with DCA intraperitoneally, but not CA, alleviated S. aureus-induced mastitis, as evidenced by DCA improving mammary injury, mammary S. aureus burden, proinflammatory markers including TNF-α, IL-1β and IL-6 and MPO activity compared with that of the S. aureus group." (PMID 36755021, 2023). "In particular IL-1β is found in greater concentration in milk of E. coli mastitis than in milk of S. aureus mastitis, and TNF-α is found in bovine milk in case of E. coli but not S. aureus mastitis." (PMID 23758654, 2013).
cognitive decline (134 papers, 2010 to 2026). "First, as a cross-sectional study, it cannot establish a clear causal relationship between aluminum exposure, IL-1β polymorphisms, and cognitive decline." (PMID 40636929, 2025). "The authors concluded that microglial activation is a major causal factor, as its removal prevented cognitive decline and reduced a broad spectrum of cytokines (IL-1α, IL-1β, IL-3, IL-4, IL-5, GM-CSF)." (PMID 41155372, 2025). "Animal experiments have shown that dexmedetomidine can reduce the inflammatory response by reducing IL-1β and NF-κB levels via α2 adrenoceptors, thereby improving the cognitive decline caused by inflammation." (PMID 36204551, 2022). "In particular, cohort studies have indicated that IL-1β, IL-6 and TNFα are involved in the alteration of nutritional status, poor physical performance, loss of muscle strength, cognitive decline, and cardiological, neurological and vascular events." (PMID 34835952, 2021). "Elevation in brain-parenchymal levels, of the proinflammatory cytokine IL-1β was previously linked to cognitive decline in murine models of dementia." (PMID 30692527, 2019). "More importantly, elevated levels of IL-1β and S-100β were associated with cognitive decline 1 w after surgery." (PMID 29249869, 2017). "In particular, microglial production of IL-1β has been associated with neuronal and capillary endothelial cell apoptosis in the retina, and cognitive decline in the brain." (PMID 26139610, 2015). "Furthermore, individuals carrying the IL-1β rs1143627G/G, rs1143643C/C, and rs16944 A/A genotypes exhibited an increased risk of cognitive decline, whereas those carrying the rs3917356C/T and T/T genotypes appeared to have a protective effect." (PMID 40636929, 2025). "Individuals carrying the IL-1β gene rs1143627G/G, rs1143643C/C and rs16944 A/A may have a higher risk of cognitive decline." (PMID 40636929, 2025). "However, some inflammatory cytokines including IL-1β and IL-6 did associate with cognitive decline and lower brain volumes in our study, suggesting that the role of inflammation needs to be investigated." (PMID 39883521, 2025). "IFNγ, as an important cytokine, can enhance the activation state of microglia, leading to the release of inflammatory mediators such as TNF-α, interleukin-1 beta (IL-1β), and nitric oxide, all of which may cause neuronal damage and cognitive decline." (PMID 39076206, 2024). "Interestingly, mRNA expression levels in the prefrontal cortex indicated a significant reduction of CD3 as well as IL-6 and IL-1β in mice exposed to menthol compared to control mice, two cytokines that have been associated with cognitive decline in humans." (PMID 37187754, 2023). "In our study, IL1B polymorphisms were associated with AD risk, pathology and cognitive decline." (PMID 36829875, 2023). "The scientists hypothesized that an increased expression of IL-1β is linked to memory impairments and accompanying cognitive decline, which could be caused by epigenetic changes brought on by SIRT1 deficiency (aging-induced) in microglia." (PMID 35893883, 2022). "Proinflammatory markers such as IL-1β and IL-6 could trigger neuroinflammation and may be associated with cognitive decline." (PMID 36494654, 2022). "IL1β is a pro-inflammatory cytokine produced by activated macrophages, and previous studies have indicated increased concentrations of IL1β are associated with AD and precede cognitive decline." (PMID 30902060, 2019). "In agreement with its pro-inflammatory profile, previous studies also proved that IL-1β has a direct influence on cortical synaptic transmission and plasticity, which may increase the risk of cognitive decline and dysfunction." (PMID 28321191, 2017). "In this study, individuals carrying the rs1143627G/G, rs1143643C/C, and rs16944 A/A genotypes exhibited significantly lower cognitive function scores, suggesting that these variants may lead to increased IL-1β expression, which in turn may heighten the risk of cognitive decline." (PMID 40636929, 2025).
cognitive decline (continued). "Consequently, it remains uncertain whether elevated IL-1β serum levels directly contribute to the cognitive decline linked to the rs1143627G/G variant." (PMID 40636929, 2025). "Thus, IL1β and T-tau could be used to assess disease severity and monitor treatment response after diagnosis in elderly people who are at risk of cognitive decline." (PMID 39109268, 2024). "Therefore, IL-1β could represent an attractive therapeutic target to attenuate brain injury and cognitive decline caused by bone fracture." (PMID 29786644, 2018). "Elevated OS markers such as 8-hydroxydeoxyguanosine (8-OHdG) correlate with cognitive decline in AD, while ROS overproduction activates pro-inflammatory cytokines (IL-1β, TNF-α), amplifying neuroinflammation via microglial activation." (PMID 40606501, 2025). "AAP up-regulated synaptic plasticity-related genes expressions, such as Snap-25 and Psd-95, and suppressed Il-1β and Tnf-α inflammatory mediators levels, effectively ameliorating high-caloric diet-induced cognitive decline in mice." (PMID 40510494, 2025). "Systemic immune challenge in AD subjects promotes neuronal damage and cognitive decline via IL-1β-induced activation of microglia and astrocytes." (PMID 40703575, 2025). "In AD progression, MG are activated to release cytokines (TNF-α, IL-1β, IL-6) and ROS, which exacerbate neuronal damage, impair synaptic function, and lead to cognitive decline." (PMID 41256774, 2025). "The strongest associations with cognitive decline in AD and MCI were detected for IL-1β and TNF-α levels." (PMID 40711681, 2025). "Persistent neuroinflammation, marked by elevated proinflammatory cytokines such as interleukin (IL)-6, IL-1β, and tumor necrosis factor-alpha (TNF-α), is strongly implicated in synaptic dysfunction, neurotransmitter dysregulation, and cognitive decline." (PMID 41020008, 2025). "Through suppressing HMGB1, the levels of TNF-α, IL-1β, and IL-6 decreased, and hippocampal atrophy and cognitive decline were attenuated in the CCH model of mice." (PMID 38231472, 2024). "This activation releases pro-inflammatory cytokines, such as TNF-α, IL-6, and IL-1β, which worsen neuroinflammation, contribute to neuronal damage, and promote cognitive decline." (PMID 38963109, 2024). "Chronic neuroinflammation has been linked to cognitive decline in VCID patients, with high expression of IL-1β and TNF-α in the hippocampus." (PMID 37208759, 2023). "A recent study explored the upregulation of inflammatory biomarkers such as TNF-α and IL-1β in people with cognitive decline." (PMID 35745147, 2022). "Targeting monocyte IL‐1β signaling to the brain represents a possible strategy to prevent cognitive decline after major surgery." (PMID 35347900, 2022). "In patients with cirrhosis and HE, proinflammatory cytokines, such as tumor necrosis factor α (TNF-α), interleukin 1β (IL-1β), and interleukin 6 (IL-6), modulate and have synergistic effects with ammonia during cognitive decline." (PMID 34937168, 2021). "Anesthesia/surgery can induce the innate immune system response and microglia activation, leading to the synthesis and release of inflammatory cytokines (e.g., TNF-α, IL-1β, and IL-6) and cognitive decline." (PMID 33541361, 2021). "The markers related to cognitive decline were classified into the following two groups: Neuroinflammatory markers: IL-1β, IL-6, tumor necrosis factor-α (TNF-α) and genetic markers (Bdnf, Arc, Egr1) which were estimated in brain regions." (PMID 33918576, 2021). "These polyphenols were evaluated on the amyloid deposits, the reactivity of microglia and astrocytes, the IL-1β production and cognitive decline." (PMID 35069106, 2021). "HMGB1 suppression with CRISPR/Cas9 knockout plasmid restored TNF-α, IL-1β, and IL-6 and attenuated hippocampal atrophy and cognitive decline." (PMID 32245271, 2020).